IL6 (interleukin 6)
Diseases named in the same sentence as IL6 in open-access papers (continued):
Sharing a sentence is not in itself a finding about the gene and the disease.
COVID-19 (continued). "Though seemingly contradictory to immune evasion mechanisms, enhanced innate immune activation, including systemic type I IFN, IL-1β, IL-6, and TNF-α production, contributes to morbidity and mortality in COVID-19." (PMID 37892134, 2023). "The exposure of CAEC to post-COVID-19 serum generates oxidant stress and stimulates CAEC to produce pro-inflammatory cytokines: IL-6, vWF, tP, and PAI-1." (PMID 38188630, 2023). "Literature-based data mining and construction of the molecular pathways revealed a total of seven genes connecting ADHD with COVID-19, including CRP, PON1, AR, OXT, IL6, TNFSF12, and IL10.." (PMID 38066446, 2023). "The focal point drawn from all these studies combined suggests the formation of a repeating cycle of GSH depletion, leading to increased levels of IL-6 and TGF-β in the state of inflammation seen in COVID-19 and HIV-positive patients." (PMID 37005767, 2023). "A small study showed that Leronlimab decreases the increased plasma levels of IL-6 and CCL5, and normalized CD4/CD8 ratios in severe COVID-19 patients." (PMID 36755327, 2023). "Much evidence showed that there are many similar inflammatory pathways between periodontitis and COVID-19, such as NF-κB pathway, NLRP3/IL-1β pathway, and IL-6 signaling pathway." (PMID 36769328, 2023). "As for the routine laboratory data, as previously shown in many studies, we found gross changes in ALT, GGT, LDH, IL-6, ferritin, and CRP are a consequence of severe COVID-19 in aged men." (PMID 36831321, 2023). "We found significantly higher levels of IL-6 (p = 0.002), IL-8 (p = 0.002), IL-10 (p = 0.006) and TNF-α (p = 0.039) in severe COVID-19." (PMID 37969879, 2023). "The COVID-19 infection instils a cytokine storm releasing pro-inflammatory cytokines like IL-6, IL-1, TNF- α and interferon which explains the abundant load of inflammatory cells in COVID-19 positive cases." (PMID 36806020, 2023). "Il-6, D-dimer, VWF, CRP, and PCT seem to be good COVID-19 biomarkers that are easy to perform in clinical practice." (PMID 37489362, 2023). "The results obtained showed that ferritin at 24 h ≥ 1225 ng/dl, IL-6 at 24 h ≥ 11 pg/ml, PaFiO2 at 72 h ≤ 164 mmHg, NLR at 24 h ≥ 22, and SOFA at 72 h ≥ 6 are the best predictors of COVID-19 mortality." (PMID 37848858, 2023). "Various cytokines (IFN-γ, IL-1β, IL-6, IL-2, and TNF-α) had altered levels in COVID-19, and the cytokine storms correlate with the severity and progression of COVID-19." (PMID 37565145, 2023). "COVID-19 patients, particularly those with severe COVID-19, show impaired antiviral responses with decreased CD3+ T cells and NK cells, reduced perforin and granzyme A expression, and increased IL-6 serum levels." (PMID 37369668, 2023). "During acute COVID-19, CRP (16.37 vs 3.5 mg/dL, P = .018) and IL-6 concentrations (130.8 vs 41.6 ng/L, P = .009) were significantly higher and Trp levels (42.2 vs 51.8 μmol/L, P = .046) lower in patients with sleeping difficulties." (PMID 37038445, 2023). "After the Spearman correlation test, a P value of <0.001 was obtained, which indicated a significant correlation between the IL-6 level and the NLR in patients with COVID-19." (PMID 38099004, 2023). "The proinflammatory proteins with the highest expressions in COVID-19 patients included: CXCL11, PD-L1, TNF, IL6, MCP3, CXL10, C XCL23, IL6 and IL8; p < 0.05." (PMID 37832397, 2023). "Altogether, eight biomarkers stood out as the main inflammatory mediators with discriminative potential between the COVID-19 (recovered/long-COVID-19) and healthy unexposed groups: IFN-γ, IL-10, IL-6, IL-2, IP-10, TNF, IL- 1β, and IL-8." (PMID 37018291, 2023). "Recent evidence shows that, in COVID-19 infection, there is an increase in the plasma cytokine levels, especially IL-6, TNF alpha, and chemokines, which have a positive correlation with COVID-19 severity." (PMID 37181975, 2023).
COVID-19 (continued). "Our results showed that COVID-19 patients had significantly higher levels of IFN-γ, TNF, IL-1β, IL-2, IL-6, IL-8, and IP-10 than the unexposed group." (PMID 37018291, 2023). "Since IL-6 is a relevant cytokine in acute respiratory distress syndrome, the blockade of its receptor with tocilizumab (TCZ) in COVID-19 patients has been evaluated in numerous studies." (PMID 37951972, 2023). "We also assessed the proinflammatory cytokine (TNF-α, IL-6, and IL-1β) levels in RBD-treated cells as COVID-19 leads to a cytokine storm." (PMID 36982738, 2023). "In a case report of a 42-year-old COVID-19 male patient, Tocilizumab (TCZ), an IL-6 inhibitor, improved his recovery." (PMID 37371870, 2023). "Five inflammatory markers were evaluated in the present study, IL-6, IL-8, IL-10, TNF-α, and CRP in hospitalized COVID-19 patients." (PMID 37111039, 2023). "Our study demonstrated that COVID-19 patients with diabetes had longer hospital stays when they exhibited elevated levels of CRP, IL-6, and CT BoD, as well as decreased PFR." (PMID 37515156, 2023). "Infiltration of lymphocytes from blood into the site of infection is directed by elevated pro-inflammatory cytokines and chemokines such as IL-6, IFNγ, MCP1 and IP-10 in the blood of COVID-19 patients." (PMID 37051070, 2023). "Most patients with severe COVID-19 show higher levels of serum pro-inflammatory cytokines such as IFN-α, IFN-γ, IL-6, IL-12, and TNF-α." (PMID 37799713, 2023). "Differences in interleukin-6 (IL-6) and neutrophil–lymphocyte ratio (NLR) levels in mild and severe COVID-19." (PMID 38099004, 2023). "Megakaryocytes can also contribute to inflammatory signaling however no upregulation of inflammatory-related genes (e.g., CCL2, CLL3, IL-6 and CXCL8, etc.)were observed in the megakaryocytes from COVID-19 patients including those with encephalopathy." (PMID 37848421, 2023). "Our study revealed a significant difference in BMI between the COVID-19 and septic shock cohorts at TP1, correlating with changes in IL-6 which we have reported earlier in sepsis cohorts." (PMID 36776891, 2023). "In recent years, it has become clear that increased levels of cytokines such as IL-1, IL-2, IL-6, GMCSF, IFN-γ and TNF-α in COVID-19 patients can lead to cell death, tissue damage and fever, and can impact vascular physiology and coagulation." (PMID 37888066, 2023). "A handful of studies have explored the measurement of biomarkers NfL, GFAP, tau proteins, IL-6, IL-10, TNF-α, and CPR during acute COVID-19 and PASC." (PMID 37545721, 2023). "Adipose macrophages produce cytokines such as interleukin-6 (IL-6) and tumour necrosis factor-alpha (TNF-α) which exacerbate the inflammatory response to SARS-CoV-2 infection and lead to severe COVID-19 in individuals with obesity." (PMID 37254139, 2023). "The predictors for in-hospital mortality of COVID-19 patients were identified to be age, congestive heart failure, obesity, COPD, prior stroke, and increased concentration of urea, LDH, CRP, IL-6, troponin I, ALT to AST ratio." (PMID 37624796, 2023). "IL-6 has been identified as an important biomarker for SARS-CoV-2 infection and COVID-19 progression." (PMID 37631998, 2023). "Severe COVID-19 is related to excessively high levels of proinflammatory cytokines (IFN-gamma, TNF-alfa or IL-6)." (PMID 36769707, 2023). "In this study, the downregulation of miR-146b was associated with an increased expression of pro-inflammatory cytokines, such as IL-6 and TNF-α, in severe COVID-19 patients." (PMID 38136554, 2023). "A meta-analysis based on the findings of fundamental and clinical research provided evidence of strong correlation between numerous inflammatory markers, especially C-reactive protein (CRP), interleukin-6 (IL-6), ESR, and severity of COVID-19." (PMID 36982809, 2023). "Higher levels of circulating IL-6, IL-10, IL-8, and tumor necrosis factor-alpha (TNF-α) were detected in non-survivors compared to survivors as well as in severe or critical COVID-19 cases." (PMID 37896963, 2023).
COVID-19 (continued). "Various inflammatory cytokines, such as interleukin IL-6, IFN-γ, and tumor necrosis factor-α, are elevated in patients with severe COVID-19." (PMID 36810114, 2023). "In the severe forms of COVID-19 and many other infectious diseases, the patients develop a cytokine storm syndrome (CSS) where pro-inflammatory cytokines such as IL-6 and TNF-α play a key role in the development of this serious process." (PMID 37951972, 2023). "There was a significant reduction in IL-6, IFN-β, and IP-10 plasma levels in COVID-19 patients at hospital admission vs. discharge." (PMID 37818368, 2023). "Meanwhile, a recent study indicated that patients with COVID-19 also showed elevated levels of cytokine profiles in their serum, including TNF-α, IL-1, IL-6, and IFN-γ24." (PMID 37363608, 2023). "In ROC analysis regarding the detection of COVID-19, DPP3 showed an AUC of 0.72 (p < 0.001; cut-off 16.4 ng/ml: sensitivity 71.7%, specificity 60.0%), opposite to IL-6 (AUC = 0.47, p = n.s)." (PMID 37733154, 2023). "Their poorer neurological status can be related to the complicated medical course from severe COVID-19 (i.e., ARDS requiring anti-IL-6 therapy), acute cardiac dysfunction, fatal ICH, and iatrogenic from heavy sedation, ventilator, and ECMO therapies." (PMID 37305142, 2023). "Other studies have shown that the administration of infliximab (anti-TNF-α antibody) reduced IL-6 and CRP levels in COVID-19 cases." (PMID 37854602, 2023). "The aim of this study was to analyze the serum concentration of interleukin-6 (IL-6), C-reactive protein (CRP), D-dimer, lactate dehydrogenase (LDH), ferritin, and procalcitonin in COVID-19 patients with different forms of the disease." (PMID 37239895, 2023). "The cytokine storm is a well-described aspect of a severe SARS-CoV-2 infection and cytokines such as IL-6 and TNF have been shown to correlate to COVID-19 severity." (PMID 37724104, 2023). "EBV viremia seems to relate to COVID-19 severity, an extended ICU stay, augmented interleukin-6 levels along with decreased CD8+ T and NK cell numbers." (PMID 36793928, 2023). "Hemophagocytosis was found to be present in the bone marrow and reticuloendothelial organs of patients with COVID-19 and elevated inflammatory markers (CRP, ferritin, IL-6, IL-8, and TNF-α), similarly to sHLH." (PMID 36983429, 2023). "Nine of ten anti-COVID-19 core targets (HIF1A, EGFR, CASP3, AKT1, MAPK1, MAPK3, HSP90AA1, mTOR, and IL-6) followed the pathways in cancer." (PMID 36817449, 2023). "In COVID-19 hearts, we identified significant upregulation of pro-inflammatory genes IL1B, IL-6, IL8, and the toll-like receptor TLR2." (PMID 36371548, 2023). "Few investigations like CRP, procalcitonin, IL-6, ESR, ferritin, chest X-ray, and CT scan are done to assess the severity and clinical score of COVID-19 patients." (PMID 36819455, 2023). "The mean scores of the monocyte count, BNB, CRP, D-Dimer, partial thrombin, PTT, IL-6, ESR, platelets, and mean corpuscular hemoglobin differed significantly between those with moderate COVID-19 severity and those with severe COVID-19 infection." (PMID 38115274, 2023). "Netakimab treatment in patients with severe COVID-19 decreased inflammation (c-reactive protein (CRP) and IL-6) and significantly improved pulmonary structure and function, leading to reduced ICU requirement and mortality rate." (PMID 37075454, 2023). "Of interest, among the significant plasma cytokines detected in COVID-19 patients, IL-8 showed a positive correlation with CD19, CD69 and ROR1 whereas IL-6 positively correlates with MFI CD24." (PMID 37207201, 2023). "Accordingly, THP-1 cells also showed an increased release of IL-6 upon SARS-CoV-2 infection, further supporting their potential role in modulating the pro-inflammatory cytokine storm observed in COVID-19 patients." (PMID 37986089, 2023).
COVID-19 (continued). "In patients with COVID-19, RDW has been shown to be correlated with IL-6 levels, as well as TNF-α, likely due to IL-6 induction of hepcidin expression, while TNF-α has been linked to erythropoietin resistance." (PMID 36829793, 2023). "High levels of IL-6 and IFN-γ observed post-COVID-19 vaccination strengthen this assumption as these cytokines, particularly IL-6, predominate in cytokine storms post COVID-19 infection." (PMID 36851240, 2023). "In the COVID-19 ARDS group, however, mild but significant positive correlations of endostatin with VE-cadherin, CRP, IL-6, and fibrinogen were detected." (PMID 37283766, 2023). "The mediators IL-1β, IL-6, IL-10, TNF-α, IL-8/CXCL8, IL-1RA, IL-18/IGIF, and sTNFR1 were all increased in patients with COVID-19 and followed the rate of elevation as clinical worsening progressed." (PMID 36851766, 2023). "In patients with severe COVID-19, which shares many characteristics with AOSD and MAS, IMs were significantly elevated and produced higher levels of IL-6 and granulocyte–macrophage colony-stimulating factor." (PMID 38124139, 2023). "Admission hepcidin, another iron-regulating molecule dependent on IL-6, was significantly higher in patients with multiple organ dysfunction (MOD) (328.7 pg/mL vs. 194.1 pg/mL) and patients with anemia in the context of COVID-19." (PMID 37763241, 2023). "Such interleukins as IL-1β, IL-6, IL-17A, TNFα, and monocyte chemoattractant peptide (MCP)-1 were identified in patients with severe COVID-19." (PMID 35213582, 2022). "A randomized, double-blind, placebo-controlled study revealed that nano-curcumin treatment reduced the serum levels of IL-1β, IL-6 and TNF-α in COVID-19 patients." (PMID 36263178, 2022). "With concern to the immune-inflammatory derangement which takes place in COVID-19, a direct link has been highlighted between viral ACE2 receptor internalization and hepcidin-IL6 activation through the NF-kB system." (PMID 35340277, 2022). "These immune cells can release a large amount of pro-inflammatory cytokines (IL-1β, IL-6, TNF-α, IL-8), which is typical in COVID-19 patients." (PMID 36296527, 2022). "We began by examining serum levels of IL-1β, IL-6, IL-10 and TNFα at ICU admission in all serum samples from our Cytokine Cohort of 90 COVID-19 patients." (PMID 36451808, 2022). "IL-6 is produced by alveolar type II (ATII) cells and activated macrophages, which is known to be a critical mediator of lung injury in COVID-19 patients." (PMID 35250984, 2022). "The results of RNA-sequencing analysis show that several inflammatory factors, including IL-6, TNF, CXCL8, CXCL2, CXCL3, CXCL10, CXCL11, and NF-κB were upregulated, which is consistent with the clinically observed phenomenon in COVID-19 patients." (PMID 36578545, 2022). "Increased levels of IL-8, IL-6, monocyte chemoattractant protein-1, and TNF-α are observed in the plasma of COVID-19 patients." (PMID 36466841, 2022). "Elevated inflammatory markers, including IL-6, CRP, ferritin, and D-dimer have been reported in severe COVID-19." (PMID 35864532, 2022). "An exaggerated release of pro-inflammatory cytokines, such as TNF-α, IL-6, IL-1, IL-8, and MCP-1, or “cytokine storm syndrome”, has been observed in severe COVID-19 patients." (PMID 35889352, 2022). "Elevated levels of IL-6 (and downstream protein CRP) are well-described as signs of poor outcome in COVID-19." (PMID 35386227, 2022). "MMP-7, TGF-β, CCL2, CCL-3, CXCL-10, G-CSF, IFN gamma, IL-10, IL-2, IL-4, IL-6, IL-7, TNF-α, IL-6, and IGF-1 were studied for their correlation with mortality in all 40 COVID-19 patients." (PMID 36286038, 2022). "The IL-6 signaling pathway is one of the key mediators of the hyperinflammatory syndrome and CRS in COVID-19." (PMID 36012968, 2022). "Serological TNF-α, IL-6, CCL4 and IL-4 levels were higher in P-COVID-19+ than in P-COVID-19-, although TNF-α was significantly higher in P-COVID-19+ than in P-COVID-19-." (PMID 35901034, 2022).
COVID-19 (continued). "Another recently published study highlights the importance for IL-6 and PCT measurement as predictive biomarkers for COVID-19 severity." (PMID 36319681, 2022). "This study aims to verify the predictive role of inflammatory biomarkers (MLR, NLR, SII, SIRI, AISI, and IL-6) and the TSS in need of invasive mechanical ventilation (IMV) and mortality in COVID-19 patients." (PMID 36140490, 2022). "In clinical applications, it has been found that severe COVID-19 patients presenting with ARDS lead to an increase in pro-inflammatory factors, most notably interleukin 1β (IL-1β), interleukin-6 (IL-6), and TNF." (PMID 35774402, 2022). "In agreement, we have reported the elevation of a wide spectrum of cytokines/chemokines including IL-6, TNF-α, IL-10, IL-12p70, IL-4, IL-15, GM-CSF, IL-17a, IL-8, IP-10, MCP-1, MIP-1α in the plasma of COVID-19 patients." (PMID 35284964, 2022). "In this study, it was found that the laboratory results of the COVID-19 pregnant patients with a mortal course - profound lymphopenia, high procalcitonin, CRP, IL-6, ferritin, AST, and LDH values - were similar to the general population with a mortal course." (PMID 35592191, 2022). "In the present study, after treatment of BEAS-2B cells with E2/GH, the IL-6, MCP-1, MDA and ROS levels were all decreased, and SOD was increased, suggesting that E2/GH treatment alleviated COVID-19-type proinflammatory responses." (PMID 36175845, 2022). "Other laboratory abnormalities, such as increased D-dimer, IL-6, and hs-CRP, were common among hyperferritinemia patients with COVID-19." (PMID 34865201, 2022). "Data analysis demonstrated an increased order of magnitude (≥3x) for CXCL8, CCL3, IL-6, IFN-γ, G-CSF and decreased order of magnitude (≤0.3x) for CCL11, IL-4, IL-5, IL-10, PDGF and IL-7 in COVID-19 patients throughout the kinetic follow-up." (PMID 36451835, 2022). "Inflammatory cytokines (IL-6, IP-10, HGF, M-CSF and CTAK) as well as pGSN were elevated in severe COVID-19 patients reminiscent of reported cytokine storms that are highly associated with increased organ damage." (PMID 36148234, 2022). "In cases of COVID-19 characterized by ARDS, IL-6 is believed to play a role in the development of cytokine storms." (PMID 36115998, 2022). "A decrease in natural killer T and B cells and increased expression of IL-2, IL6, IL10, TNF-α, and interferon-γ (INF-γ) were observed in the COVID-19 pathophysiology." (PMID 35656183, 2022). "IL-6 and TNF-α levels were statistically different in the four age groups between COVID-19 patients and healthy controls; P=0.036 and P=<0.001, respectively." (PMID 36381078, 2022). "Nevertheless, ongoing clinical trials are evaluating the efficacy and safety of this drug in COVID-19 (NCT04486521), (NCT04329650) (Martinez, 2022; Anti-IL6 and Corticosteroid Monotherapy, 2022)." (PMID 36091800, 2022). "Levels of cytokines such as IL-6 and TNF-α increase rapidly, dysregulating the immune response and leading to direct myotoxicity in COVID-19." (PMID 36140656, 2022). "Pro-inflammatory cytokines IL-6, TNF-α, IL-8, IL-1α, anti-inflammatory cytokine IL-4, and the IP-10 chemokine were induced in the severe presentation of COVID-19 during pregnancy." (PMID 36016660, 2022). "Additionally, it could also be speculated that interleukin-6 may not be a potentially actionable target cytokine to treat COVID-19-associated cytokine storms." (PMID 36705224, 2022). "An increased concentration of IL-6, TNF-α, IL-2, IL-8, IL-1β, G-CSF, IL-17, GM-CSF, IL10, MCP1, MIP1α, chemokines, galectins in serum, was detected in COVID-19 patients." (PMID 35075140, 2022). "Although CRP is inadequate indicator for treatment of COVID-19 because CRP production by IL-6 pathway is suppressed by TCZ, LDH, which indicates lung injury and severity of COVID-19, also showed a decreasing trend." (PMID 34436742, 2022). "Network pharmacology analyses identified 6 potential targets (IL6, DPP4, MIF, PRF1, SERPING1, and SLC6A4) for emetine in anti-LUAD/COVID-19." (PMID 35733175, 2022).